IL10 (interleukin 10)
Diseases named in the same sentence as IL10 in open-access papers (continued):
Sharing a sentence is not in itself a finding about the gene and the disease.
Allergy (continued). "IL-10 has immunosuppressive functions and can modulate the activity of several cell subsets involved in allergic reactions, such as mast cells, Th2 T cells, eosinophils, and DCs." (PMID 28589115, 2017). "For a possible future therapeutic application of antigen-activated Breg cells against e.g. allergic diseases, it is crucial to confirm the IL-10-inducing effect in human B cells." (PMID 28753651, 2017). "All Th2-related cytokines (IL-4, IL-5, IL-10, and IL-13) were increased by the allergy induction and inhibited by baicalein." (PMID 27561877, 2016). "It is not possible to use an in vivo interventional approach in humans to study the role of IL-10 in the protective mechanism behind H. pylori-mediated protection from allergy." (PMID 27014260, 2016). "The systemic IL-10+ Treg response is therefore likely to play a role in H. pylori-mediated protection against allergy in humans." (PMID 27014260, 2016). "Overall, the risk factors for allergies in children of the present cohort included a reduced percentage of CD4+CD25+FOXP3+ T cells, reduced FOXP3 expression, and PPG-stimulated IL-10 secretion." (PMID 27646403, 2016). "IL-10 is known to be protective against allergy, acting via inhibition of antigen presentation, down-regulation of effector T-cell cytokine expression, and inhibition of mast cell degranulation." (PMID 27014260, 2016). "Previous studies had shown that IL-10 played an important role in the inhibition of Aspergillus induced allergic reactions in ABPA." (PMID 27312383, 2016). "It is reported that the IL-10+ BCs had immune regulatory function and the frequency of IL-10+ BC was less in several immune disorders, including allergic diseases, which can be restored by specific allergen immunotherapy." (PMID 27825134, 2016). "Ag-specific immunotherapy in allergy to house dust mite, birch pollen, bee venom, and grass pollen 31–33 is characterized by an increase in IL-10-producing T cells." (PMID 25627813, 2015). "IL-10 secretion by Th2 cells is important in restraining Th2 responses in murine allergy 8 and Th2-derived IL-10 can act on DCs to prevent further differentiation of Th2 cells." (PMID 25627813, 2015). "Histamine upregulates Th2 cells proliferation and production of Th2 cytokines, such as IL-4, IL-5, IL-10, and IL-13, and thus drives to development of allergies." (PMID 25960757, 2015). "IL-10 is essential for protection from immunopathology, allergy, and autoimmunity and is expressed by a wide variety of innate and adaptive immune cells 1,2." (PMID 25627813, 2015). "The induction of T-regulatory cells (Treg) by AIT is central to the suppression of the allergic reaction: Treg produce IL-10 which is able to suppress IgE production by B cells and to induce IgG4." (PMID 26213608, 2015). "A study in mice has shown that IL-10 is also produced by mast cells, counteracting the inflammatory effect that these cells have at the site of an allergic reaction." (PMID 25923079, 2015). "IL-10 appears to be an important cytokine in the success of specific immunotherapy in allergy since it has been described to be increased in blood and affected tissues of treated patients." (PMID 24465795, 2014). "The protective effects of H. pylori against allergy are also mediated by secretion of regulatory T cells (Tregs) that suppress immunity and inflammation via bystander effects of IL-10." (PMID 24528371, 2014). "The role of IL-10 in the pathogenesis of allergic diseases during treatment and its level changes in the serum are currently the subject of controversial discussion." (PMID 24995021, 2014). "Th2 cells mainly secrete IL-4, IL-5, IL-6 and IL-10, which are involved in humoral immune and allergic reactions." (PMID 24520300, 2014). "Several common polymorphisms have been identified in the promoter region of both cytokines, including −1082G>A and −592C>A for IL10 and −509C>T for TGFB genes, some of these polymorphisms being associated with allergic diseases." (PMID 25759826, 2014).
Allergy (continued). "Immune regulatory Th2 cytokines, such as IL-4, IL-6, and IL-10, which favor humoral immunity, mediate allergic diseases, control chronic infections, and promote adaptive immunity." (PMID 25264680, 2014). "This relationship was dysregulated in allergy, with the Th2: Th1 ratio maintained at higher levels and the IL-10 response abrogated." (PMID 23521868, 2013). "In splenocyte cultures, BM4 treatment led to the induction of the allergy-suppressing cytokines IL-10 and IFN-γ, accompanied by a suppression of IL-5 and IL-13 levels." (PMID 24175303, 2013). "In mouse models of allergy, it is clear that IL-10 plays an important role in mediating successful antigen-specific therapeutic tolerance." (PMID 23755052, 2013). "Meanwhile, C44 is more suitable than C48 in the context of allergic diseases, based on its attenuated Th2 (IL-5, IL-6 and IL-10) potential." (PMID 23554802, 2013). "For example, S. mansoni-induced regulatory B cells can attenuate allergic disease through an IL-10-dependent mechanism." (PMID 23349889, 2013). "Successful allergen-specific immunotherapy (SIT) in man, for example in the treatment of grass pollen or house dust mite allergies, correlates with generation of IL-10-secreting CD4+ T cells." (PMID 23755052, 2013). "In murine models of allergic airway inflammation many infections or products from the infectious microorganisms protect from the development of allergy by inducing the production of regulatory cytokines such as IL-10 and TGF-β." (PMID 22952678, 2012). "Such non-specific effects on the host systemic immune response would be predicted to have effects on other inflammatory conditions such as allergy in which IL-10 is considered to have an important modulatory role." (PMID 22848773, 2012). "T regulatory cell-derived IL-10 has a well-documented role in immune homeostasis in the lung during allergy." (PMID 22563306, 2012). "In such allergic disease, S. mansoni antigens downmodulate the Th2 exacerbated inflammatory response in vitro by inducing the production of IL-10 and the expression of the regulatory molecules, CTLA-4 in T lymphocytes." (PMID 23209879, 2012). "Tregs play a central role in the regulation of autoimmune, infectious, and allergic diseases by cell-to-cell contact-dependent inhibition and by the secretion of anti-inflammatory cytokines such as IL-10 and TGF-β." (PMID 23118775, 2012). "In recent years, many studies on the use of probiotics in the prevention or treatment of allergy have focused on their role, by acting on monocytes, PBMCs or DCs, in the production of IL-10 and in the generation of regulatory cells." (PMID 21533162, 2011). "Tr1 regulatory cells produce IL-10 and play a critical role in the suppression of allergic diseases." (PMID 22216160, 2011). "Third, while across all children the sensitivity to allergy reflected increased levels of IL-16 and IL-10, the latter showed a significant inverse relationship to measures of S100B in the ADHD group." (PMID 20509936, 2010). "This induction of IL-10-secreting cells has now also been shown to be a dominant feature of successful allergen-SIT in a range of allergies [4,5,11••,15,16]." (PMID 20850958, 2010). "In patients with both types of allergy i.e. skin and rhinitis, there was a positive correlation of IL-5 with IL-10 and that of IL-6 with TNF α." (PMID 20616938, 2010). "The possibility of a regulatory role for IL-10 in allergic subjects has been indicated in HDM allergy, where patients who produce more IL-10 had smaller wheal sizes in skin prick tests." (PMID 23282404, 2008). "Opposite to this, however, has been the demonstration that children with early and persistent allergy have more disease and higher Th2 cytokine responses than children with late-onset allergy and that they also have higher IL-10 responses." (PMID 23282404, 2008). "One of iTreg-cell types is the IL-10-producing type 1 Treg (Tr1) cells, whose suppressive function has been well documented in allergy and autoimmunity." (PMID 23283296, 2008).
Allergy (continued). "In summary, based on the available evidence, QES likely exerts its therapeutic effects on allergic reactions by reducing mast cell activation, suppressing type 2 cytokines, attenuating eosinophilic responses, enhancing IL-10 levels, and alleviating allergy-induced inflammation." (PMID 40005039, 2025). "Our findings revealed that IL-10 may protect against AR by reducing plasma lactate levels, providing a mechanistic link between immune regulation and metabolic alterations in allergic diseases." (PMID 40570726, 2025). "IL-4 and IL-13 are involved in the inflammatory process of allergic reactions by regulating Th2 cell differentiation and stimulating IgE production by B cells, while IL-10 inhibits Th1 cell activation and proliferation, shifting the immune response to the Th2 type." (PMID 40038782, 2025). "Additionally, IL‐10 has been shown to play a role in response to allergy, a common comorbidity of CRS and potential trigger for COPD exacerbation, by dampening Th2‐derived allergic inflammation." (PMID 36780897, 2023). "The expression of the pro-inflammatory cytokine IL-4, which was increased in the allergy model group, was significantly suppressed by fructan administration, and the expression of the anti-inflammatory cytokine IL-10 was significantly increased upon Kes administration." (PMID 37737162, 2023). "It was also shown that methylation profile of IL4, IL5, IL10, IFNG and FOXP3 was associated with environmental exposures and the direction of methylation dynamics differed depending on the presence and types of allergy symptoms." (PMID 37520545, 2023). "Both naturally occurring thymus-derived regulatory T cells and inducible regulatory T cells suppress the development of allergic diseases mainly mediated by the suppressive cytokines IL-10 and TGF-β, and other studies have demonstrated that Tregs can also produce IFN-γ." (PMID 38106504, 2023). "Mesenchymal cells, which regulate IL-10 production by ILC2s, might be a potential treatment target in allergic diseases." (PMID 36941691, 2023). "Additionally, enhancement of Th1/Treg responses with more secretion of IFN-γ or IL-10 will be beneficial to restrict allergic diseases, leading to a decreased ratio of Th2/Th1 in the 100 ng/mL SEB group." (PMID 37368664, 2023). "Mast cell-derived IL-10 has been shown to alleviated severe cutaneous contact hypersensitivity reactions, and IL-33, an alarming signal in the allergic diseases and inflammation, could activate mast cells and trigger downstream reactions." (PMID 38012745, 2023). "Interestingly, circulating KLRG1+ ILC2s from individuals with allergic disease were unable to generate IL-10, but this ability was recovered after effective allergen immunotherapy." (PMID 36960063, 2023). "However, the allergy inducers—LPS and poly(I:C)—downregulate the expression of anti-inflammatory IL-10 in HNEpC that is restored to normal levels after treatment with ELVN-34 (panel IL-10)." (PMID 35057008, 2022). "Furthermore, B cells activation and IgA and IgG1 secretion provoked by IL-6 and IL-10 lead to allergy symptoms reduction." (PMID 35812388, 2022). "As already emphasized, Treg cells produce IL-10, IL-35, and TGF-β, three main immunosuppressive cytokines with pleiotropic functions which play key roles in protecting the host from infection-associated immunopathology, autoimmunity, and allergy." (PMID 36431972, 2022). "Human Tregs produce IL-10 and TGF-β, two main pleiotropic immunosuppressive cytokines which play key roles in protecting the host from infection-associated immunopathology, autoimmunity, and allergy." (PMID 35745713, 2022). "This important capacity of EcO83 to promote IL-10 secretion could contribute to the observed lower allergy incidence in the group of S AM." (PMID 36703968, 2022). "Possibly, induction of IL-10+ PCs by BA in early life might be an effective way to protect against allergy and autoimmunity, especially in the long run." (PMID 35333906, 2022).
Allergy (continued). "In the context of allergy, a clinical study on African children reported that IL-10 is induced by chronic schistosomiasis and that it is inversely correlated with reactivity in a house dust mite skin test, suggesting that IL-10 plays a central role in the helminth-mediated suppression of atopy." (PMID 35113966, 2022). "Moreover, elevation of IL-10 in patients after successful specific allergy immunotherapy highlights the importance of IL-10 in controlling allergic disease development." (PMID 36703968, 2022). "IL-10 is an important regulatory cytokine required to control allergic diseases." (PMID 35812388, 2022). "On the other hand, the anaphylaxis patients may have had impaired IL‐10 production or regulatory immune functions, resulting in impaired production of IgG4 that would mitigate IgE‐mediated allergic reactions." (PMID 36086810, 2022). "CpG-ODN have been demonstrated to stimulate IL-10-producing B cells and have shown the capacity to prevent and reverse allergic immune reactions in several animal models, indicating their potential as a preventive and active treatment for allergic disease." (PMID 36009677, 2022). "There is increasing evidence that the IL-10 produced by ILCs suppresses immune responses and could be helpful, such as in allergic disease, or harmful, such as in the setting of cancer, to patients." (PMID 36275689, 2022). "Notably, AUF1s were also dispensable for the alternative polarization of macrophages by IL4, TGFβ and IL10, known to be engaged in allergic reactions." (PMID 35222366, 2022). "Elevated IL-10 levels were found after immunotherapy for bee-venom allergies." (PMID 34804031, 2021). "However, allergy sufferers expressed mainly PD-L1 and IL-10 in the infected tissues, with a strong correlation between PD-L1 and IL-10 in the polarization." (PMID 34769327, 2021). "DOCK8-deficient B cells show diminished responses to TLR9 signaling, suggesting a possible defect in IL-10-producing Breg cells in those with DOCK8 deficiency, which may contribute to allergies." (PMID 34867940, 2021). "Treg cells generally release TGF-β and IL-10 to suppress other Th cells, and the function of Treg may be impaired in allergic disease." (PMID 34360939, 2021). "Studies have highlighted the role of IL-10 in the immune regulation of allergic diseases and AIT." (PMID 34804031, 2021). "Therefore, patients with allergic disease display a tendency to produce fewer tolerogenic IL-10-producing DCs." (PMID 35387059, 2021). "For instance, Il-10 produced by mast cells expand mast cells by autocrine and limit leukocyte infiltration and epidermal hyperplasia, indicating the protective role of mast cells against allergy." (PMID 32235696, 2020). "Additionally, the administration of SHE inhibited the mRNA expression levels of allergy mediating cytokines, IL-6, IL-10, and IFN-γ in HDM/DNCB stimulated mice." (PMID 32824648, 2020). "On the basis of the mouse model, we found viridicatol to alleviate the allergy symptoms; decrease the levels of specific immunoglobulin E, mast cell protease-1, histamine, and tumor necrosis factor-α; and promote the production of interleukin-10 in the serum." (PMID 33081290, 2020). "In addition, IL-10 produced by TReg cells orchestrates antibody production in allergies from IgE toward IgG4." (PMID 33123017, 2020). "Although mono-colonization with both EcN-Ctrl and EcN-Chim reduced allergy in poly-sensitized mice, only the mono-colonization with EcN-Ctrl triggered the increased expression of IL-10 (P < 0.01), Foxp3 (P < 0.001), and IFNγ (P < 0.0001) mRNA in the lung as compared to GF poly-sensitized control." (PMID 33679699, 2020). "In line with present observations, HDM/DNCB stimulation upregulated the T-bet, STAT3, and GATA3 and other allergy mediating cytokines (IL-4, IL-5, IL-10, IL-13, and IFN-γ) and chemokine (TARC) expression levels, while these were dose-dependently downregulated following SHE treatment." (PMID 32824648, 2020).